NLRP3 (NLR family pyrin domain containing 3)
Diseases named in the same sentence as NLRP3 in open-access papers (continued):
Sharing a sentence is not in itself a finding about the gene and the disease.
diabetic retinopathy (continued). "The possible impact of topiramate against diabetic retinopathy (DREN) and its molecular mechanisms in relation to the nod-like receptor family pyrin domain containing 3 (NLRP3) inflammasome has not been studied before." (PMID 38137423, 2023).
cognitive decline (61 papers, 2017 to 2026). "The older adults were followed up for 2 years to investigate the relationship between NLRP3 SNPs and risk of cognitive decline." (PMID 41507841, 2026). "Zinc activates microglia to promote neuroinflammation, and zinc deficiency accelerates cognitive decline by activation of the NLRP3 inflammasome." (PMID 38648940, 2024). "Their data also demonstrated that zinc deficiency accelerated cognitive decline by potentiation of NLRP3-dependent inflammation in an APP/PS1 mouse model of AD." (PMID 38648940, 2024). "Their seminal study showed that NLRP3 ablation prevented thymic involution, brain astrogliosis, bone loss, and cognitive decline." (PMID 39301197, 2024). "We demonstrated that the cognitive decline induced by zinc deficiency was completely abated in the APP/PS1 mice deficient in NLRP3." (PMID 33597269, 2021). "APP/PS1 mice deficient in NLRP3 were protected against the accelerated cognitive decline with zinc deficiency." (PMID 33597269, 2021). "In cerebral small vessel disease (CSVD), NLRP3 inflammasome activation in microglia is closely associated with blood-brain barrier disruption, white matter injury, and cognitive decline, with the inflammatory pathway it mediates potentially playing a central role in the pathogenesis of CSVD." (PMID 40552323, 2025). "Thus, the protective effects of genetic knockout of the NLRP3 inflammasome suggest a new therapeutic strategy for age-associated cognitive decline and for slowing down CNS aging." (PMID 38068904, 2023). "Indeed, interest has now moved towards examining peripheral signatures of NLRP3 activation in individuals at increased risk of AD, free from established cognitive impairment in order to identify those at greater risk of later cognitive decline." (PMID 36311713, 2022). "Therefore, the inflammatory response dependent on NLRP3 is closely related to the cognitive decline associated with Aβ excessive deposition." (PMID 33204250, 2020). "Traditionally, the cognitive decline associated with AD was attributed to the accumulation of amyloid and tau but emerging evidence suggests that neuroinflammation driven by and triggering additional Nlrp3 inflammasome activation is another critical contributor to AD pathology." (PMID 33071950, 2020). "In human neuronal cells and APPSWE/PS1ΔE9 murine model of AD, infection induces Aβ accumulation, NLRP3 activation, neuroinflammation and cytotoxicity, and chronic infection exacerbates neuropathology and cognitive decline." (PMID 41571675, 2026). "Collectively, these findings emphasize the significance of NLRP3 as both a pathogenic factor and a therapeutic target in managing HIV-related cognitive decline." (PMID 41280902, 2025). "Studies have demonstrated that dexmedetomidine exerts neuroprotective effects against postoperative cognitive decline via the NLRP3 inflammasome signaling pathway." (PMID 39857699, 2025). "This inflammatory environment, with activation of the NLRP3 inflammasome and release of pro-inflammatory cytokines, promotes the chronic neuroinflammatory state, exacerbating neuronal damage and cognitive decline." (PMID 40285014, 2025). "The NLRP3/IL‐1β signaling axis is increasingly recognized as a critical link between metabolic disorders and cognitive decline." (PMID 40589337, 2025). "In summary, our findings demonstrate that prolonged HFD consumption exacerbates tau phosphorylation and NLRP3 inflammasome activation in the brain, leading to cognitive decline in 3xTg‐AD mice." (PMID 40589337, 2025). "Although the clinical trials are still in an early phase, these NLRP3 inhibitors show potential effects in reversing cognitive decline by regulating microglial activation and reducing neuroinflammatory cascades." (PMID 41516057, 2025). "Blockade of the NLRP3 inflammasome signaling reduces Aβ deposition and alleviates cognitive decline in 5xFAD mice after HSV-1 infection." (PMID 39026249, 2024).
cognitive decline (continued). "A critical contributor to cognitive decline progression is neuroinflammation, which is driven and triggered by NLRP3 inflammasome activation." (PMID 39109268, 2024). "Administration of MCC950 sodium, a selective small-molecular inhibitor of the NLRP3 inflammasome, reduced Aβ deposition and ameliorated cognitive decline in 5xFAD mice following HSV-1 infection." (PMID 39026249, 2024). "Preoperative administration of TUDCA downregulated the expression of GRP78 and XBP1 and inhibited NLRP3 inflammasome activation and neuroinflammation, thereby exhibiting an obvious therapeutic effect against postoperative cognitive decline." (PMID 39432407, 2024). "It was also highlighted that dysregulated glucose metabolism and impaired mitochondrial function contribute to NLRP3 inflammasome activation, neuroinflammation, and cognitive decline in AD." (PMID 38068904, 2023). "Further longitudinal studies are warranted to examine the contribution of peripheral NLRP3 responses towards disease pathology and as cognitive decline accelerates in T2DM." (PMID 36311713, 2022). "Results obtained in transgenic Tau22/Asc−/− and Tau22/Nlrp3−/− mice showed a considerable reduction of tau phosphorylation with reduced cognitive decline, which indicates that NLRP3 is an important mediator of Aβ–induced tau pathology." (PMID 34209586, 2021). "MCC950 was found to effectively block NLRP3 inflammasome activation and protect against cognitive decline, motor deficits, and neurodegeneration in TX mice." (PMID 33462188, 2021). "Here, we show that neuroinflammation and cognitive decline in MPSIIIA are driven by a two‐step IL‐1‐dependent immune response mediated by the NLRP3 inflammasome." (PMID 32057196, 2020). "They found that genetically inhibiting NLRP3 activity in Tau22/Asc−/− and Tau22/Nlrp3−/− mice significantly reduced tau phosphorylation in different brain regions and prevented cognitive decline in these mice." (PMID 32296063, 2020). "For this reason, our data showed that the NLRP3 inflammasome inhibitor Bay11-7082 blocked the stimulating effects of KA on the production and deposition of Aβ as well as the cognitive decline in APP23 mice." (PMID 31182681, 2019). "NLRP3 knockout significantly suppressed amyloidosis and neuropathology and alleviated the cognitive decline in AD experimental animals." (PMID 31182681, 2019). "Additionally, another study found that aggregates of β-amyloid and tau proteins activated NLRP3 inflammasome signaling in the brain, contributing to both pathophysiological changes and cognitive decline in AD." (PMID 40232008, 2025). "Cerebral IH may convert astrocytes from A2 (protective) to A1 (injurious) via NLRP3 immunoenzymes, resulting in hippocampal neuronal disorders and cognitive decline." (PMID 40767426, 2025). "Furthermore, another notable bioactive compound within ginseng extract, Compound K, has demonstrated its capability to inhibit NLRP3 inflammasomes and contribute to the mitigation of neuronal and cognitive decline." (PMID 40152069, 2025). "Additionally, TL1A can promote A1 differentiation of reactive astrocytes via NLRP3 inflammasome activation, while aggravating postoperative cognitive decline." (PMID 39432407, 2024). "Notably, the effect was reversible, as zinc supplementation protected APP/PS1 mice against cognitive decline by inhibiting NLRP3 inflammasome activation." (PMID 38648940, 2024). "Notably, NLRP3 knockout prevented age-related and diet-accelerated astrogliosis and cognitive decline, illustrating NLRP3’s significant role in these processes." (PMID 39301197, 2024). "Furthermore, recent reports posit that the NLRP3 inflammasome is essential for Aβ and Tau pathology and leads to cognitive decline in mice." (PMID 38720773, 2024). "Our results suggest that NLRP3 inflammasome may drive the development of AD in the HSV-1 infection condition, and inhibition of NLRP3 signaling have potential to prevent Aβ accumulation and cognitive decline of AD." (PMID 39026249, 2024).
cognitive decline (continued). "NLRP3 inflammasome may be an ideal target for preventing against cognitive decline and neurodegeneration." (PMID 38284892, 2024). "Therefore, it is likely that slowing aging through various NLRP3 inhibition mechanisms will lessen the corresponding cognitive decline during aging." (PMID 38068904, 2023). "Therefore, it is likely that slowing aging through various NLRP3 inhibition mechanisms will lessen the corresponding cognitive decline with aging." (PMID 38068904, 2023). "CUMS induced depressive-like behaviors and cognitive decline in mice, which could be reversed by inhibiting NLRP3 inflammasome." (PMID 37165444, 2023). "In addition, copper treatment increased NLRP3 expression, and NLRP3 knockdown mitigate neurodegeneration and cognitive decline in ATP7B knockout mice." (PMID 37928399, 2023). "Our data therefore suggests no role for peripheral NLRP3 responses in the early stages of T2DM-associated cognitive decline." (PMID 36311713, 2022). "The present study showed that Aβ activates Syk and deactivates downstream AMPK, which mediates excessive mitochondrial fission and leads to activation of the microglial NLRP3 inflammasome, resulting in cognitive decline, amyloid plaques, and neurofibrillary tangles." (PMID 35474599, 2022). "Therefore, NLRP3 silencing suppresses copper-induced neuroinflammation and protects TX mice against progressive motor deficits and cognitive decline by eliminating NLRP3 inflammasome activation." (PMID 33462188, 2021). "This study may be the first to exhibit the bridge between oxidative stress and NLRP3-mediated neuroinflammation in postoperative cognitive decline induced by surgery/sevoflurane." (PMID 30918581, 2019). "CONCLUSIONS: Our study suggested that genetic variations of NLRP3 could affect inflammatory gene expression, transcriptional activity and interaction between gene and miRNA, and therefore were associated with the risk of MCI and cognitive decline." (PMID 41507841, 2026). "Experimental studies in Tau transgenic mice have demonstrated that genetic deletion or pharmacological inhibition of NLRP3 or its adaptor protein ASC results in reduced Tau phosphorylation and mitigated cognitive decline." (PMID 40806766, 2025). "Neuronal injury and cognitive decline in HAND happen through a complex process involving chronic microglial activation, NLRP3 inflammasome activation, and disruption of the BBB by HIV-1 proteins Tat and gp120." (PMID 40285014, 2025). "This knowledge gap underscored the need to investigate whether Cp infection and NLRP3 inflammasome activation occur in the AD retina, explore potential interactions during both early and advanced stages of AD, and examine their correlations with brain pathology and cognitive decline." (PMID 40667156, 2025). "Inhibition of NLRP3 inflammasome effectively alleviated CUMS-induced depressive-like behaviors and cognitive decline in mice, and inhibited the activation of AD physiological indicators." (PMID 37165444, 2023). "Yet despite strong evidence that NLPR3 associated responses may be linked with the detrimental inflammatory characteristics of this disease, whether this NLRP3 hyper-responsiveness seen in T2DM may be related to the risk of cognitive decline and AD in T2DM, has not been explored." (PMID 36311713, 2022). "Blocking NLRP3 inflammasome activation with siNlrp3 or MCC950 reduced interleukin-1β and interleukin-18 production, thereby effectively mitigating cognitive decline, locomotor behavior impairment, and neurodegeneration in TX mice." (PMID 33462188, 2021). "The development of NLRP3 -/- x APP/PS1 transgenic rodent models demonstrates that by reducing inflammation in AD models, histopathology hallmarks and cognitive decline can be mitigated." (PMID 32033164, 2020). "Elevated NLRP3 expression correlated with higher GDS scores, suggesting that inflammasome activation may contribute to cognitive decline in this population." (PMID 41280902, 2025).
cognitive decline (continued). "Studies in rodents lacking NLRP3 or caspase-1 have shown protection from neuroinflammation and cognitive decline." (PMID 39125762, 2024). "Inhibition of NLRP3 inflammasome could alleviate CUMS-induced depressive-like behaviors and cognitive decline in mice, and inhibit the activation of AD physiological indicators." (PMID 37165444, 2023). "Given the potential role of NLRP3 in mediating the link between T2DM and later cognitive decline, we tested whether there was any relationship between the subtle neuropsychological decrements seen in midlife T2DM and peripheral NLRP3 inflammasome responses." (PMID 36311713, 2022).
steatosis (61 papers, 2013 to 2025). Increased lipid within the cytoplasm of cells. "In this study, we evaluated the possible pathogenic roles of NLRP3 and IL-1β in the development of steatosis and fibrosis in patients with MAFLD." (PMID 39179677, 2024). "The NLRP3 inflammasome has been implicated in steatosis, inflammation, and fibrotic processes in the liver according to a significant amount of evidence from experimental models." (PMID 39179677, 2024). "The diagnostic performance of serum NLRP3 as a potential biomarker for liver necroinflammation, fibrosis, and steatosis was assessed by plotting the ROC curve." (PMID 36376416, 2022). "The present study showed an association between NLRP3 levels in serum and the liver and the grade of steatosis in HCV-infected patients as also previously demonstrated in patients with NAFLD17,19,33,53–55." (PMID 36376416, 2022). "The receiver operating characteristic curve analysis revealed a high diagnostic performance of serum NLRP3 in determining the extent of liver necroinflammation, fibrosis, and steatosis (area under the curve = 0.951, 0.971, and 0.917 respectively, P < 0.001)." (PMID 36376416, 2022). "The in vivo findings revealed that adiponectin deficiency aggravated HFD-induced liver injury and steatosis as well as stimulated NLRP3 inflammasome activation." (PMID 33251225, 2020). "NLRP3 deficiency prevents the development of alcohol-induced liver inflammation and has a beneficial effect on liver damage and steatosis." (PMID 31595205, 2019). "Some studies have suggested that NLRP3 deficiency exacerbates liver damage and steatosis in mice." (PMID 39605303, 2024). "NF-κB signaling in macrophages may play an important role in TCDD-induced changes in metabolism via NLRP3 inflammasome activation which has been associated with the progression of steatosis to steatohepatitis." (PMID 37789023, 2023). "Although deficiencies of NLRP3 were shown to attenuate alcohol-associated steatosis, a study showed that this inhibition can increase the rate of hepatic damage, suggesting that the NLRP3 inflammasome complex may be protective during alcohol-induced hepatic damage." (PMID 34916977, 2021). "However, in a similar alcohol-related liver diseases mouse model with a deficiency for NLRP3, steatosis, inflammation, IL-1β expression, and number of activated natural killer T cells are all decreased, highlighting NLRP3 role in the pathogenesis of alcohol-related liver disease." (PMID 34650994, 2021). "This beneficial action of FTZ through the inhibition of NLRP3 inflammasome activation was not only associated with suppression of liver inflammation and HSCs activation leading to fibrogenesis but also with the early event of lipid deposition triggering steatosis." (PMID 30140364, 2018). "Oxidative stress, NLRP3 inflammasome activation, and gut-liver axis perturbations further exacerbate steatosis and inflammation." (PMID 40475995, 2025). "DHA has also been shown to inhibit NLRP3 inflammasome activation in the liver, thereby reducing inflammation and preventing the progression from simple steatosis to steatohepatitis." (PMID 40219010, 2025). "For example, atorvastatin reduces inflammation by blocking the NLRP3 inflammasome pathway, and long-term use can alleviate liver inflammation, steatosis, and hepatocellular damage." (PMID 40244398, 2025). "H&E staining and ELISA for liver LPS revealed that Nlrp3−/− mice had increased hepatocyte steatosis, lymphocyte infiltration and liver LPS levels relative to WT mice." (PMID 39605303, 2024). "Studies have shown that uric acid induces hepatic fat accumulation, oxidative stress, and activation of the NLRP3 inflammasome, linking uric acid to steatosis and inflammation." (PMID 37299406, 2023). "The activation of the NOD-like receptor protein 3 (NLRP3) inflammasome triggers pyroptosis, thus propelling the progression from simple steatosis to NASH." (PMID 37731666, 2023).